KLK6 (kallikrein related peptidase 6)
Diseases named in the same sentence as KLK6 in open-access papers (continued):
Sharing a sentence is not in itself a finding about the gene and the disease.
tumor (continued). "Western blot analysis revealed that Ki67 and VEGF1 protein levels were decreased, and cleaved caspase-3 protein levels were increased in tumor tissues from KLK6−/− mice injected with B16F10 cells compared to WT mice." (PMID 36552865, 2022). "Upregulation of KLK6 correlated also with the depth of tumor invasion, presence of distant metastasis, and as an independent marker to predict poor disease-free and survival rate in CRC patients." (PMID 35883559, 2022). "KLK6−/− mice injected with B16F10 or LLC cells showed significantly less tumor volume and weight than the WT mice." (PMID 36552865, 2022). "Inhibition of KLK6 by siRNA exhibits the tremendous antineoplastic activities by suppressing tumor growth and inducing cell apoptosis of BLCA cells." (PMID 36193495, 2022). "We also analyzed the expression of KLK6 and selected co-expressed genes in the subset of colonic organoids developed from the patients’ surgical tissue (paired normal and tumor cultures)." (PMID 34065672, 2021). "The identified families of genes, encoding keratins, extracellular matrix proteins, protein trafficking and TGF-β, FOS, and Ser/Thr protein kinase proteins contribute to tumor progression, cell invasion, and metastasis in KLK6-overexpressed CRCs." (PMID 34065672, 2021). "Using a set of 7 patient derived tumor organoid cultures, we confirmed the variability in expression and secretion of KLK6, and the necessity of an individualized approach in designing the CRC chemotherapy." (PMID 34065672, 2021). "In this study, we aimed to investigate the biochemically proposed KLK network in PDAC using patient-derived samples and the tumour-biological role of KLK6 in human PDAC cells." (PMID 34439122, 2021). "In search for other KLK6-expressing cell types, we conducted a correlation analysis using the TCGA PDAC dataset and found that KLK6 correlated with tumour-associated genes present in the stroma and immune cells." (PMID 34439122, 2021). "We also assessed the secreted KLK6 in the conditioned media of organoids derived from the normal and tumor tissues." (PMID 34065672, 2021). "The expression of KLK6 was significantly higher in all tumor areas compared to the normal tissues (p = 0.001, normal vs. descending tumors, p = 1.6 × 10−6, normal vs. ascending tumors)." (PMID 34065672, 2021). "We found several kallikrein-related peptidases that were upregulated, in particular kallikrein-related peptidase 6 at the forefront of the tumour area." (PMID 34439122, 2021). "Well-differentiated ducts harbour very low levels of KLK6, while undifferentiated tumours, with nuclear atypia and single-cell invasion, tend to have a higher KLK6 expression." (PMID 34439122, 2021). "Following KLK6 inhibition, KLK6 mRNA expression; metabolic activity, indicative of cell viability; and secretion of KLK6 were reduced in our tumour spheroids, while the secretion of cathepsin D and uPA was increased." (PMID 34439122, 2021). "Our findings indicate that the treatment of tumour spheroids with a proteolysis-resistant KLK6 inhibitor modified their mRNA expression, metabolic activity and secretion of KLK6 and other tumour-associated proteases." (PMID 34439122, 2021). "Other studies demonstrated that KLK6 played an important role in many non-neoplastic diseases, such as inflammatory and degenerative illnesses, as well as trauma lesions of the central nervous system." (PMID 34858488, 2021). "The elevated levels of secreted KLK6 were detected in the tumor cultures compared to normal ones and they increased with the time in culture." (PMID 34065672, 2021). "The APPI-4M KLK6 inhibitor was reported to act like a functional inhibitor blocking tumour cell functions, such as cell migration." (PMID 34439122, 2021). "We analyzed RNA levels of KLK6 and the selected co-expressed genes from the set depicted in a correlation plot in the paired normal and tumor organoid cultures." (PMID 34065672, 2021).
tumor (continued). "KLK6-targeted inhibition reduced KLK6 mRNA expression, secretion and metabolic activity of tumour spheroids, which in part modified its tumour-biological role in cell dissemination." (PMID 34439122, 2021). "KLK6 mRNA was chosen because it is ectopically expressed in CRC tumor in contrast to CEACAM5 and MUC2 that are expressed at similar levels in CRC tumors and normal colon." (PMID 32049988, 2020). "KLK6 staining in the crypt area of the tumor samples was significantly higher than in the morphologically normal tissue at 10 cm away from the tumor." (PMID 31692974, 2019). "KLK6 expression resulted in significant downregulation of vimentin, a critical marker of epithelial-to-mesenchymal transition of tumour cells." (PMID 31186631, 2019). "In conclusion, we showed that KLK6 displays a concentration‐dependent effect on breast primary tumor growth and metastasis." (PMID 30980596, 2019). "The proteome of parental (PAR) and engineered MDA‐MB‐231 cells expressing low or high KLK6 levels was analyzed by HPLC‐MS/MS to identify putative molecular pathways underlying the observed, tumor suppression or promotion, respectively." (PMID 30980596, 2019). "KLK6, a member of the kallikrein, was able to predict tumor recurrence in epithelial ovarian carcinoma." (PMID 31866765, 2019). "Specifically, when KLK6 is expressed at levels comparable to the levels secreted by normal mammary cells, it inhibits primary tumor formation and lung metastasis in vivo." (PMID 30980596, 2019). "Tumor, paired adjacent, and apparently normal tissue blocks were sectioned sequentially and processed for KLK6 and HMGA2 staining." (PMID 31692974, 2019). "We show that KLK6 inhibits both primary tumor growth and lung metastases only when re‐expressed at normal levels." (PMID 30980596, 2019). "Postmortem analysis showed that 80% of mice injected with KLK6 wt 5 clone developed tumors and 37.5% of tumor-bearing mice produced liver metastasis." (PMID 31692974, 2019). "KLK6, a member of the secreted serine protease family of protein-cleaving enzymes, is also defined as an epigenetically regulated tumour suppressor." (PMID 31186631, 2019). "In the context of HNSCC, a recent study provided experimental evidence that silencing of KLK6 activates the EMT program accompanied by a mesenchymal-like cell morphology as well as accelerated tumor cell migration and invasion." (PMID 28671620, 2017). "The loss of KLK6 in HNSCC seems to create a mesenchymal-like morphology and accelerated motility of tumor cells with an EMT-phenotype, identified by loss of E-cadherin and prominent induction of vimentin expression in HNSCC cells." (PMID 28671620, 2017). "Silencing in FaDu cells and ectopic expression in HeLa cells unraveled an inhibitory function of KLK6 on tumor cell proliferation and mobility." (PMID 25990935, 2015). "Following transfection of FaDu cells with control (FaDu-Mock) or pRS-KLK6-shRNA vectors (FaDu-shKLK6), we established stable clones as loss-of-function model to gain a deeper insight into the molecular role of KLK6 on tumor relevant processes." (PMID 25990935, 2015). "Evaluation of KLK6 expression concerning the relative amount of positive tumor cells and the staining intensity revealed a final expression score for 162 patients, including 115 OPSCCs and 47 LSCCs." (PMID 25990935, 2015). "Kaplan-Meier survival analysis indicated that patients with KLK6-IR < 10, KLK6 percent tumor core stained < 3, or KLK7-IR < 9 had a significantly improved survival." (PMID 26231762, 2015).
tumor (continued). "In the current study, we conducted loss-of-function and gain-of-function approaches in mucosal tumor cell lines to investigate the contribution of KLK6 in the regulation of tumor development and malignant progression." (PMID 25990935, 2015). "Consistent with most reports, we found high KLK6 expression in primary tumor samples of 42.6 % HNSCC patients." (PMID 25990935, 2015). "We demonstrate that silencing of KLK6 expression promotes tumor cell proliferation, migration and invasion in vitro." (PMID 25990935, 2015). "Multivariable analysis of KLK6 % tumor core stained showed a significant correlation with survival, utilizing gender and ECOG as covariates (HR = 1.93, CI = 1.03–3.63, P = 0.04)." (PMID 26231762, 2015). "Stable clones of human mucosal tumor cell lines were generated with shRNA-mediated silencing or ectopic overexpression to characterize the impact of KLK6 on tumor relevant processes in vitro." (PMID 25990935, 2015). "Conversely animals with tumours expressing a combination of KLK6/10 behave differently than their single expressing counterparts suggesting that the kallikreins can interact." (PMID 22102857, 2011). "Paradoxically, the KLK6/10 group also had on average a higher tumour burden (p<0.01), likely because of the longer ascites-free survival." (PMID 22102857, 2011). "For example, all subtypes express KLK6, with perhaps a slightly higher proportion of clear cell tumours that display strong immunostaining for KLK6." (PMID 22102857, 2011). "Despite the apparent differences in the molecular oncogenesis of low- and high-grade serous tumours, their upregulation of KLK6 suggests a common pathway is activated in both types of tumours." (PMID 19707197, 2009). "Like in immunohistochemistry of native tumour, KLK6 expression in cell lines was more distinct than that of KLK10." (PMID 18854834, 2008). "KLK10 and KLK6 are members of the kallikrein family of 15 known proteases in humans, which play an emerging role in tumour microenvironment, invasion and angiogenesis." (PMID 18854834, 2008). "Probably future studies including more patients can prove a use for KLK6 or KLK10 as tumour biomarkers in PDAC." (PMID 18854834, 2008). "We categorised KLK6-positive and KLK6-negative patients according to clinicopathologic variables including tumour stage, grade, histotype, debulking success and response to chemotherapy." (PMID 17242704, 2007). "We assessed KLK6 mRNA expression in tumours with high or low KLK6 protein concentration and correlated these two parameters." (PMID 17242704, 2007). "For statistical analysis, natural logarithm was taken for the expression levels of KLK6 in tumour cells relative to normal HOSE cells." (PMID 15305183, 2004). "KLK6-positive tumor cells might foster an immunosuppressive TME by driving fibroblast-to-myofibroblast differentiation, enhancing extracellular matrix (ECM) deposition, and inhibiting CD8+ T cell infiltration." (PMID 41383634, 2025). "Meanwhile, we identified KLK6 as a potential promoter of tumor progression and immunosuppression." (PMID 41383634, 2025). "Mechanistically, KLK6-positive tumor cells might foster an immunosuppressive TME by driving fibroblast-to-myofibroblast differentiation, enhancing extracellular matrix (ECM) deposition, and inhibiting CD8+ T cell infiltration." (PMID 41383634, 2025). "Consequently, a self-sustaining vicious cycle is established: KLK6-positive tumor cells drive fibroblast-to-myofibroblast differentiation, which in turn secrete excessive ECM components." (PMID 41383634, 2025). "Additionally, KLK6 plays a role in the tumor microenvironment by stimulating production of tumor necrosis factor alpha (TNF-α) through the activation of protease-activated receptor 1 (PAR-1)." (PMID 39594797, 2024).
tumor (continued). "Although the exact mechanism of upregulation of KLK6 and other proteases in the presence of APC mutations is not completely understood, our study contributes to the recognition of KLK6’s role in tumor development and demonstrates a possibility for using KLK6 for CRC detection and therapy." (PMID 39594797, 2024). "The role of KLK6 on cell growth was evaluated using a subcutaneously implanted tumor model." (PMID 36193495, 2022). "Our findings suggest that KLK6, by enhancing the multicellular aggregation may facilitate the formation of cancer cell emboli in vivo (in blood vessels) or tumor cell clusters in malignant peritoneal ascites." (PMID 35883559, 2022). "However, KLK6-related pathways are focused on the preclinical stage and represent the prospective therapeutic targets to prevent tumor progression." (PMID 36193495, 2022). "Moreover, the TNF-α protein levels were increased in macrophages isolated from the tumor tissues of WT mice injected with B16F10 cells compared to KLK6−/− mice." (PMID 36552865, 2022). "Although we cannot exclude the possibility of the effect of other microenvironmental factors and inflammatory cytokines on TNF-α production in a tumor microenvironment, these results suggest that the KLK6/PAR1 axis is critical, at least in part, for TNF-α production by macrophage." (PMID 36552865, 2022). "Moreover, CXCL1 inhibition rKLK6-mediated tumor growth and metastatic lung module formation in KLK6−/− mice injected with B16F10." (PMID 36552865, 2022). "It is also conceivable that tumor microenvironmental conditions could play a role in the activation of pro-KLK6, as tumors are known to acidify their microenvironment, which results in the activation of secreted enzymes." (PMID 35883559, 2022). "We generated KLK6−/− mice to investigate the role of KLK6 in the tumor microenvironment." (PMID 36552865, 2022). "Because KLK6 expression is detected in macrophages, we hypothesized that macrophages might affect KLK6-mediated tumor growth." (PMID 36552865, 2022). "This study aimed to determine the role of KLK6 in the tumor microenvironment." (PMID 36552865, 2022). "We then correlated KLK6 expression with tumour, stroma and immune cell areas." (PMID 34439122, 2021). "Further differential expression analysis was done between KLK6-high group and the rest of the CRC cases to determine whether any specific genes were altered in KLK6-high group compared to all other samples in the tumor dataset." (PMID 34065672, 2021). "In line with another study, we found KLK6 expressed in tumour-adjacent cells." (PMID 34439122, 2021). "Tumor Samples from the CRC patients with significantly elevated KLK6 transcript levels were identified in the RNA-Seq data from Cancer Genome Atlas (TCGA) and their expression profiles were evaluated using Gene Ontology (GO), Phenotype and Reactome enrichment, and protein interaction methods." (PMID 34065672, 2021). "Furthermore, KLK6 expression in CRC correlated significantly with increasing tumor stage and histological grade and was connected with a more advanced Dukes’ stage, liver metastasis, and poor prognosis." (PMID 32630086, 2020). "Therefore, re‐expression of KLK6 at physiological levels reduces the expression of gelatinases that strongly correlate with tumor metastasis and progression." (PMID 30980596, 2019). "Very recently, we showed that KLK6 accelerates nonmelanoma skin cancer formation in vivo by increasing tumor‐associated inflammation." (PMID 30980596, 2019). "Despite numerous studies pointing to a critical role of KLK6 during neoplastic transformation and malignant progression, more recent data questioned its general tumor-promoting role and stressed the importance of considering its context-dependent function, as exemplified in breast and renal cancer." (PMID 28671620, 2017). "However, the underlying mode of action and putative proteolytic downstream targets of KLK6 implicated in EMT and tumor cell plasticity remain to be elucidated." (PMID 28671620, 2017).
tumor (continued). "To determine whether differential KLK6 expression affected AF-induced autophagic cell death and autophagy processes, we analyzed tumor sections using H&E staining and IHC for KLK6." (PMID 27863404, 2016). "Recent studies showed that KLK6 upregulation is a strong marker of advanced tumor stage." (PMID 27863404, 2016). "AF treatment decreased the tumor volume for both mock and KLK6-overexpressing cells." (PMID 27863404, 2016). "However, recent studies questioned the general oncogenic role of KLK6 and stressed the importance to consider its context-dependent, tumor-protective function, as exemplified in breast and renal cancer." (PMID 25990935, 2015). "Also, the mean percent tumor core stained was significantly higher in grade IV relative to grade III for KLK6 (P = 0.0005, Kruskal-Wallis test)." (PMID 26231762, 2015). "They provided compelling evidence that KLK6 may act as suppressor for tumor progression by promoting a mesenchymal-to-epithelial transition." (PMID 25990935, 2015). "Finally, we performed IHC staining on serial tumor sections to investigate inverse regulation of KLK6 and Vimentin as well as intracellular accumulation of β-catenin in tumor cells with KLK6low expression levels." (PMID 25990935, 2015). "In addition, high tumor levels of KLK7-IR, were, like KLK6, found to be associated with reduced patient survival." (PMID 26231762, 2015). "Moreover, as the percent of the tumor core stained positive for KLK6 or KLK9 increased, survival decreased (HR = 1.63, CI = 1.06–2.50, P = 0.03 and HR = 2.25, CI = 1.21–4.22, P = 0.01, respectively)." (PMID 26231762, 2015). "Indeed, HeLa-KLK6 clones had a significantly reduced tumor cell growth in comparison to HeLa-Mock controls." (PMID 25990935, 2015). "All of these suggest that KLK6 may be a potential biomarker in predicting tumor recurrence and therapeutic target for them." (PMID 23587030, 2013). "KLK6 may play a protective role against tumor progression by inhibiting the epithelial-to-mesenchymal transition." (PMID 22436421, 2012). "Similarly, mice xenografted with cells overexpressing KLK10, 5/6, 5/10, 6/10 had a significant survival advantage over their respective control mice, while mice with KLK6-secreting tumours had significantly decreased survival." (PMID 22102857, 2011). "Together, these data suggest that Ras-Raf mutations may increase the invasive potential of these borderline tumours through increased expression of KLK6." (PMID 19707197, 2009). "We identified RCC-specific features including enhanced T cell exhaustion, pro-angiogenic and immunosuppressive MC polarization, and a malignant CASC15+KLK6+ epithelial subpopulation that may drive tumor progression through MIF and CD99-mediated intercellular communication." (PMID 40932351, 2026). "Moreover, The IHC score of KLK6 was positively related to tumor size (R = 0.45, p = 0.03)." (PMID 41383634, 2025). "It has also been shown that KLK6 triggers tumor cells and parenchymal cells in the TME and that the metastasis‐promoting activity of KLK6 may be mediated by its ability to degrade extracellular matrix proteins and E‐cadherin in parallel to the epithelial‐to‐mesenchymal transition (EMT)." (PMID 37609678, 2023). "Additionally, KLK6 expression seems to correlate with tumour differentiation." (PMID 34439122, 2021). "Additionally, KLK6 expression was found in tumor adjacent epithelial and stromal cells, and may considerably contribute to the aggressiveness of cancer cells by a paracrine mode of action." (PMID 25990935, 2015).